MALAT1 (metastasis associated lung adenocarcinoma transcript 1)
Diseases named in the same sentence as MALAT1 in open-access papers (continued):
Sharing a sentence is not in itself a finding about the gene and the disease.
atherosclerosis (59 papers, 2014 to 2025). A disease characterized by the build-up of fatty material and calcium deposition in the arterial wall resulting in partial or complete occlusion of the arterial lumen. "Long non-coding RNA metastasis-associated lung adenocarcinoma transcript 1 (lncRNA MALAT1) was demonstrated to play a role in atherosclerosis pathogenesis." (PMID 39273193, 2024). "For instance, in an apolipoprotein E (apoE)-knockout mouse model, MALAT1 deficiency accelerated inflammation and atherosclerosis." (PMID 37509544, 2023). "Here, we reported that lncRNA Metastasis-associated lung adenocarcinoma transcript 1 (Malat1) was down-regulated in various vascular diseases including arteriovenous fistula, artery injury and atherosclerosis." (PMID 37022488, 2023). "Another lncRNA studied in the pathogenesis of atherosclerosis is metastasis-associated lung adenocarcinoma transcript 1 (MALAT1)." (PMID 36187570, 2022). "In vivo experiments suggested an association between atherosclerosis progression and decreased MALAT1 content in VECs-exosomes." (PMID 34869682, 2021). "Long non-coding RNA metastasis-associated lung adenocarcinoma transcript 1 (MALAT1) has a protective effect against atherosclerosis lesions." (PMID 34552965, 2021). "In another study, exosomes extracted from oxidized LDL treated HUVECs resulted in metastasis-associated lung adenocarcinoma transcript 1 (MALAT1)-induced NETs formation and atherosclerosis progression." (PMID 34359859, 2021). "Another interesting lncRNA in atherosclerosis is MALAT1 (metastasis-associated lung adenocarcinoma transcript 1)." (PMID 32772181, 2020). "For example, heterozygous MALAT1-deficient ApoE-/- mice have increased inflammation and atherosclerosis." (PMID 30838214, 2019). "MALAT1 has been implicated in functional regulation of a variety of cells involved in atherosclerosis, such as vascular endothelial cells, smooth muscle cells and macrophages." (PMID 30871555, 2019). "Recently, a few lncRNAs, such as GAS5, NEAT1 and MALAT1 were reported to be associated with regulating atherosclerosis progression and prognosis." (PMID 30873207, 2019). "In ApoE −/− heterozygous mice with MALAT1 deficiency, an increased level of inflammation and the development of atherosclerosis were observed." (PMID 31212708, 2019). "MALAT1 deficiency was found to promote atherosclerosis and plaque inflammation." (PMID 39798064, 2025). "Additionally, MALAT1 deficiency in certain mouse models has been linked to accelerated macrophage inflammation and atherosclerosis." (PMID 38473915, 2024). "Thus, loss of MALAT1 expression in ox-LDL-treated VECs- derived exosomes lead to the maturation of DCs in the development of atherosclerosis." (PMID 34869682, 2021). "Furthermore, immune-mediated atherosclerosis was reported to be directly caused by a deficiency of the MALAT1 lncRNA in apolipoprotein E (ApoE)-/- mice." (PMID 34638541, 2021). "Considering that MALAT1 has been largely associated with both atherosclerosis and autophagy, that the miR-17-92 cluster is greatly involved in these two processes, and that its expression is directly regulated by MALAT1, analyzing this relationship in depth may yield interesting results." (PMID 36230953, 2022). "It is also secreted as a cfRNA, and exosomal MALAT1 was found to affect the formation of “neutrophil extracellular traps” (=decondensed extracellular neutrophil chromatin) in a mouse model of atherosclerosis." (PMID 40283676, 2025). "MALAT1 plays a crucial role in controlling atherosclerosis by modulating the number and activities of inflammatory cells." (PMID 38791545, 2024). "In diabetic atherosclerosis models, a cinnamic acid derivative reduces inflammasome activation and pyroptosis by suppressing MALAT1." (PMID 38473915, 2024). "Circulating lncRNAs have become potential biomarkers of atherosclerosis in diagnostic, prognostic, and predictive tools, such as ZFAS1, HOTAIR, MALAT1." (PMID 37371830, 2023).
atherosclerosis (continued). "In diseases that SMCs regenerate like vascular injury and atherosclerosis, Malat1 expression level is down-regulated; while in diseases that SMCs are reduced or lost contractile phenotype, Malat1 is up-regulated." (PMID 37022488, 2023). "In vitro analyses revealed that these beneficial effects of sinapic acid originate from its ability to suppress the expression of MALAT1, which promotes pyroptotic cell death in macrophages and, consequently, the progression of atherosclerosis." (PMID 37509544, 2023). "Previous studies on atherosclerosis have shown that there are a variety of lncRNAs, including MALAT1, H19, ATB, LEF1-AS1, and ZEB1-AS1, which are promising therapeutic targets." (PMID 35028010, 2022). "A recently published study suggested a direct role for MALAT1 in the development and progression of atherosclerosis and demonstrated that MALAT1 exhibits anti-inflammatory properties in part by inhibiting miR-503 expression in vivo." (PMID 36187570, 2022). "MALAT1−/+ ApoE−/− mice suffered accelerated atherosclerosis despite normal diet compared to ApoE−/− mice." (PMID 36552736, 2022). "We previously found NEAT1−/− and MALAT1−/− mice to display massive atherosclerosis and vascular inflammation." (PMID 36552736, 2022). "Preconditioning with ox-LDL, HUVECs exhibit low expression levels of MALAT1 promoting DCs maturation and atherosclerosis development." (PMID 34692785, 2021). "Metastasis-associated lung adenocarcinoma transcript 1 (MALAT1), a long non-coding RNA has been widely shown to be involved in tumorigenesis, but the role of exosomal MALAT1 in atherosclerosis is likely to be controversial." (PMID 34513963, 2021). "Involved in tumorigenesis, Metastasis- associated lung adenocarcinoma transcript-1 (MALAT1) is a long non-coding RNA (lncRNA), and its downregulation promotes atherosclerosis." (PMID 34869682, 2021). "In-vitro and in-vivo experiments explored the effect of exosomal MALAT1 in the maturation of DCs and subsequently in the progression of atherosclerosis." (PMID 34869682, 2021). "In ox-LDL treated HUVECs co-cultured with neutrophils, MALAT1 in EVs acts as a regulator increasing NETs formation and trigger hyperlipidemia and inflammatory responses, which in turn exacerbate atherosclerosis." (PMID 34692785, 2021). "Simultaneously, the MALAT1 expression level was significantly decreased in patients with atherosclerosis and oxLDL-stimulated THP-1 macrophages." (PMID 34940525, 2021). "Only a few studies show that lnc-MALAT1 expression is reduced in central nervous system tissues from multiple sclerosis patients and carotid plaques from atherosclerosis patients." (PMID 33111743, 2020). "A recently published study elucidated the in vivo role of MALAT1 in atherosclerosis and demonstrated that MALAT1 exhibits anti-inflammatory properties in part by binding to miR-503." (PMID 32772181, 2020). "Only one study reports that lnc-MALAT1 high expression is associated with prolonged main adverse cardiovascular and cerebrovascular events (MACCE)-free survival in atherosclerosis patients." (PMID 33111743, 2020). "The atherosclerosis model was established by feeding ApoE−/− mice with high-fat diet, and the levels of lncRNA MALAT1 in mouse arterial tissue were detected by RT-qPCR." (PMID 30871555, 2019). "The ubiquitously expressed and evolutionarily conserved lncRNA, MALAT1, is decreased in atherosclerotic plaques, and reduced MALAT1 levels in hematopoietic cells promotes atherosclerosis and inflammation in mice in vivo." (PMID 30838214, 2019). "Reduced expression of MALAT1 in hematopoietic cells contributes to the development of atherosclerosis and inflammation in mice in vivo." (PMID 31212708, 2019). "We found that MALAT1 was dysregulated in arterial tissues from ApoE−/− mice with high-fat food-induced atherosclerosis and human umbilical vein endothelial cell line (HUVECs) stimulated with ox-LDL." (PMID 30871555, 2019).
atherosclerosis (continued). "Rare studies have been conducted to investigate the exact interactions between lung adenocarcinoma transcript 1 (MALAT1), thymocyte selection-associated high mobility group box (TOX), and miRNAs in the pathogenesis of atherosclerosis (AS)." (PMID 31949884, 2019). "Collectively, these data highlight the importance of MALAT1 in the development and progression of atherosclerosis." (PMID 30871555, 2019). "MALAT1 is closely related to endothelium function in atherosclerosis through the regulation of endothelial cell proliferation and migration." (PMID 30305120, 2018). "Earlier, it has been reported that MALAT1 may have a role in the etiology of atherosclerosis by acting as an influential atherosclerosis repressor via sponging miR-155 in human coronary artery endothelial cells (HCAECs)." (PMID 39798064, 2025). "Although a recognized significant correlation between MALAT1 and miR-155 was previously stated in various pathological conditions such as atherosclerosis and hypoxia of cardiac stem cells, the clinical relevance of this correlation in BD remains to be analyzed." (PMID 39798064, 2025). "Moreover, it has been suggested that MALAT1 influences lipid metabolism disorders, inflammatory responses, and progression of atherosclerosis by regulating ox-LDL-related macrophages." (PMID 39273193, 2024). "Another study reveals that MALAT1 regulates ox-LDL-associated macrophages, influencing lipid metabolism and linking to inflammatory reactions, contributing to the pathological progression of atherosclerosis." (PMID 38791545, 2024). "Thus, the findings of these studies indicate that MALAT1 expression is upregulated in macrophages by stimulating agents, such as oxLDL, and MALAT1 enhances atherosclerosis by inducting lipid uptake, foam cell formation, and cell death in macrophages." (PMID 37509544, 2023). "Furthermore, decreased MALAT1 levels have been detected in the serum of patients with atherosclerosis and in oxLDL-treated THP-1 cells." (PMID 37509544, 2023). "NEAT1-/- and MALAT1-/- mice display massive atherosclerosis and vascular inflammation." (PMID 36615135, 2023). "Mice devoid of NEAT1 or MALAT1 displayed immune disturbances affecting monocyte-macrophage and T cell differentiation, and an immune system highly vulnerable to stress stimuli and prone to the development of atherosclerosis." (PMID 37998395, 2023). "The upregulation of MALAT1 alleviated apoptosis and inflammation and reduced atherosclerosis." (PMID 38132140, 2023). "In humans, MALAT1-lncRNA is recognized as a biomarker for atherosclerosis." (PMID 37486375, 2023). "The reason for the discrepancy in the role of MALAT1 in atherosclerosis remains unknown; thus, additional analyses are warranted." (PMID 37509544, 2023). "Using single cell RNA sequencing data (GSE117963) from atherosclerosis mice models, we assessed Malat1 levels in Sca1+ SPCs and SMCs in atherosclerosis, in which SMCs greatly regenerate to form lesions and play indispensable roles throughout its pathological process." (PMID 37022488, 2023). "For instance, MALAT1 was upregulated in patients with atherosclerosis, while its suppression protected the endothelium from oxLDL-induced inflammation and oxidative stress by upregulation of miR-181b and downregulation of thymocyte selection-associated high mobility group box." (PMID 35906216, 2022). "Additionally, MALAT1 in EVs shuttles from ECs into recipient DCs and ameliorates the development of atherosclerosis." (PMID 34692785, 2021). "It is likely that the direct interactions between MALAT1 and NEAT1 through the enzymatically MALAT1‐derived mascRNA might promote the development of atherosclerosis." (PMID 33080104, 2020). "MALAT1 can inhibit atherosclerosis development through several mechanisms." (PMID 33154191, 2020).
atherosclerosis (continued). "As for the correlation of lnc-MALAT1 with disease severity and inflammation in neurological and cerebrovascular disease patients, only one study shows that elevated lnc-MALAT1 expression is correlated with less advanced lesions in atherosclerosis patients." (PMID 33111743, 2020). "Thus, we performed further in vitro studies to elucidate the role of MALAT1 in EndMT process of atherosclerosis." (PMID 30871555, 2019). "In this study, we tested the influence of lncRNA MALAT1 on atherosclerosis in vivo." (PMID 30787203, 2019). "As a result, lncRNA MALAT1 inhibition attenuates atherosclerosis in mice." (PMID 30787203, 2019). "Our study revealed that the pathological EndMT required the activation of the MALAT1-dependent Wnt/β-catenin signaling pathway, which may be important for the onset of atherosclerosis." (PMID 30871555, 2019). "Next, we detected MALAT1 expression in aortas upon atherosclerosis induction." (PMID 30871555, 2019). "However, contrary reports exist regarding the role of MALAT1 in atherosclerosis." (PMID 38473915, 2024). "However, there are reports of an opposite role played by MALAT1 in atherosclerosis." (PMID 37509544, 2023). "Therefore, MALAT1 might have the potential, in addition to its beneficial role in atherogenesis, to accelerate atherosclerosis via autophagy stimulation, in which it inhibits the contractile phenotype of VSMCs." (PMID 36082127, 2022). "Additionally, MALAT1 in EVs from HUVECs treated with ox-LDL exhibit lower expression compared with EVs from HUVECs without stimuli, an indication that the loss of MALAT1 in EVs promotes DCs maturation in atherosclerosis." (PMID 34692785, 2021). "Thus, in addition to its beneficial role in atherogenesis, MALAT1 might have the potential to accelerate atherosclerosis by inhibiting the contractile phenotype of VSMCs via autophagy stimulation." (PMID 33154191, 2020). "Finally, we tested the role of lncRNA MALAT1 on atherosclerosis in vivo." (PMID 30787203, 2019). "In atherosclerosis and CAD patients, MALAT1 levels rise more than two-fold and subsequently fall after treatment." (PMID 38473915, 2024). "In essence, exosomal MALAT1 from ox-LDL-treated endothelial cells triggers NETs formation, thereby exacerbating atherosclerosis." (PMID 39502508, 2024). "It is intriguing that certain lncRNAs, such as MALAT1 and HOTAIR, have been identified to play conflicting roles in atherosclerosis." (PMID 38473915, 2024). "LncRNA MALAT1 was found to regulate the expression of NLRP3, and upregulation of MALAT1 exacerbated NLRP3-mediated cellular pyroptosis in diabetic rat atherosclerosis." (PMID 38439031, 2024). "The lncRNA MALAT1 has emerged as a biomarker for CVD, and recent research suggests its involvement in the development of atherosclerosis." (PMID 38791545, 2024). "It was observed that in atherosclerosis patients and oxLDL-treated THP-1 cells, MALAT1 levels decrease." (PMID 38473915, 2024). "In this study, we investigated the expression levels of Malat1 in conditions that generate SMCs, including AVF, arterial injury and atherosclerosis (AS)." (PMID 37022488, 2023). "Their further in vivo experiments showed the loss of MALAT1 from ox-LDL-VECs-Exos in mouse repressed the nuclear factor erythroid 2-related factor (NRF2) signaling pathway and failed to inhibit dendritic cells maturation, which might be associated with atherosclerosis progression." (PMID 34513963, 2021). "Interestingly, lncRNA MALAT1 and NEAT1 have been found to serve as novel immunoregulators affecting monocyte‐macrophage functions and their disruption may contribute to identifying high risk in post‐MI and atherosclerosis patients." (PMID 33080104, 2020). "Furthermore, MALAT1 may serve as potential biomarkers of atherosclerosis." (PMID 30787203, 2019).
atherosclerosis (continued). "Silencing MALAT1 has been shown to reduce endothelial inflammation induced by oxidized low-density lipoprotein (LDL) and protect the endothelium from oxidative stress, both critical factors in atherosclerosis development." (PMID 38791545, 2024). "Only a few lncRNA are well-conserved among species, one of them being MALAT1, which blocks numerous miRNAs by providing non-functional binding sites and plays a crucial role in atherosclerosis and autophagy." (PMID 36230953, 2022). "Together, circRNA circDENND1B and the considered above lncRNA MALAT1, CHROME, GAS5, MEG3 function as ceRNAs and bind miRNAs that suppress the expression of ABCA1, which increases the level of ABCA1 mRNA and prevents the development of atherosclerosis." (PMID 34940525, 2021). "Thus, lncRNA MALAT1 affects the expression of SCARB1 as a result of interaction with other proteins, contributes to its transcription activation, and prevents atherosclerosis development." (PMID 34940525, 2021). "This is in line with previous studies, demonstrating that MALAT1 is upregulated in macrophages and HUVECs treated with ox-LDL, and in proliferative vascular smooth muscle cells, all of which are critical cells for atherosclerosis." (PMID 30871555, 2019). "For example, interactions among MALAT1, NEAT1, and key immune effector molecules could regulate the development of atherosclerosis." (PMID 30873207, 2019). "Thus, increasing the levels of CHROME, MeXis, MALAT1, lincRNA-p21, or LEENE and inhibiting the activity of LSTR or ANRIL can be used in the treatment of disorders of lipid metabolism and atherosclerosis." (PMID 31212708, 2019). "Mice lacking the lncRNAs NEAT1 or MALAT1 displayed immune disturbances affecting monocyte-macrophage, as well as T cell differentiation, rendering the immune system highly vulnerable to stress stimuli, thereby promoting the development of atherosclerosis." (PMID 36615135, 2023). "Mice lacking lncRNAs NEAT1 or MALAT1 displayed immune disturbances affecting monocyte-macrophage and T cell differentiation and rendering the immune system highly vulnerable to stress stimuli, thereby promoting the development of atherosclerosis." (PMID 36552736, 2022).